SERHL (serine hydrolase like (pseudogene) )
Synonyms: BK126B4.1; BK126B4.2; HS126B42; SERHLP; dJ222E13.1
Gene: Long non-coding RNA gene on chromosome 22 (42,500,254 to 42,512,564, forward strand). Ensembl gene ENSG00000293485.
Diseases named in the same sentence as SERHL in open-access papers:
SERHL is named in the same sentence as 5 diseases in open-access papers, as found by Europe PMC text mining. Sharing a sentence is not in itself a finding about the gene and the disease. The quoted sentences say what the papers report.
hepatocellular carcinoma (1 paper, 2022). A malignant tumor that arises from hepatocytes. "SERHL is hypothesised to be involved in peroxisome function and was shown to be part of a lncRNA signature that predicts recurrence-free survival in hepatocellular carcinoma." (PMID 35205253, 2022).
Tetralogy of Fallot (1 paper, 2018). A congenital cardiac malformation comprising pulmonary stenosis, overriding aorta, ventricular septum defect, and right ventricular hypertrophy. "SERHL was found in tetralogy of Fallot patients and was associated with DNA methylation abnormalities." (PMID 30532766, 2018).
tumor (1 paper, 2020). "They demonstrated that MSC-AS1, POLR2J4, EIF3J-AS1, SERHL, RMST, and PVT1 were significantly upregulated in tumor samples compared to nontumor samples and were significantly associated with RFS." (PMID 33520012, 2020).
SERHL also shares sentences with these, for which no sentence is quoted: cancer (1 paper); neuroblastoma (1).